PTTG1 (PTTG1 regulator of sister chromatid separation, securin)
Description:
Probably acts by blocking the action of key proteins. During the mitosis, it blocks Separase/ESPL1 function, preventing the proteolysis of the cohesin complex and the subsequent segregation of the chromosomes. At the onset of anaphase, it is ubiquitinated, conducting to its destruction and to the liberation of ESPL1. Its function is however not limited to a blocking activity, since it is required to activate ESPL1. May also play a role in DNA repair via its interaction with Ku, possibly by connecting DNA damage-response pathways with sister chromatid separation.
Synonyms: hPTTG; EAP1; PTTG; TUTR1; securin; ECRAR
Tractability: PROTAC: UniProt records ubiquitination sites on it; ubiquitination databases record sites on it.
Gene: Protein-coding gene on chromosome 5 (160,421,816 to 160,428,748, forward strand). Ensembl gene ENSG00000164611.
Subcellular location: Cytoplasm; Nucleus
Subcellular location (Human Protein Atlas): Cytosol; Nucleoli
Pathways (Reactome):
Cell Cycle: APC/C:Cdc20 mediated degradation of Securin; APC/C:Cdh1 mediated degradation of Cdc20 and other APC/C:Cdh1 targeted proteins in late mitosis/early G1; Separation of Sister Chromatids
Gene Ontology:
Molecular function: molecular function activator activity; protein binding; cysteine-type endopeptidase inhibitor activity
Biological process: homologous chromosome segregation; maintenance of meiotic sister chromatid cohesion; maintenance of mitotic sister chromatid cohesion; spermatogenesis; chromosome organization
Cellular component: cytosol; nucleus; separase-securin complex; cytoplasm
Genetic constraint (gnomAD): Loss-of-function variants: 7 observed, 19.54 expected, observed/expected ratio (o/e) 0.36, 90% interval 0.2 to 0.67. The upper end of that interval is the gene's LOEUF score, 0.67, which puts it in group 2 of 6, group 1 being the genes least tolerant of losing a copy. Missense variants: 195 observed, 246.24 expected, observed/expected ratio (o/e) 0.79, 90% interval 0.7 to 0.89. Synonymous variants: 78 observed, 90.71 expected, observed/expected ratio (o/e) 0.86, 90% interval 0.71 to 1.04.
Homologues: Orthologues: chimpanzee PTTG1 (99% identical), macaque PTTG1 (99% identical), dog PTTG1 (84% identical), guinea pig Pttg1 (78% identical), mouse Pttg1 (72% identical), rat Pttg1 (71% identical), tropical clawed frog XB5905938 (37% identical), zebrafish pttg1 (30% identical). Paralogues in human: PTTG2 (81% identical).
Diseases named in the same sentence as PTTG1 in open-access papers:
PTTG1 is named in the same sentence as 148 diseases in open-access papers, as found by Europe PMC text mining. Sharing a sentence is not in itself a finding about the gene and the disease. The quoted sentences say what the papers report.
breast carcinoma (50 papers, 2005 to 2025). "PTTG1 is also overexpressed in breast tumors and breast cancer stem cells and is associated with a high tumor grade, lymphatic metastasis, and poor outcomes of breast cancer cases." (PMID 41009526, 2025). "Although many studies have demonstrated the roles of overexpressing PTTG1 in breast cancer metastasis, the mechanisms underlying regulation of PTTG1 expression are still unclear." (PMID 33250768, 2020). "For example, PTTG1 has been implicated in breast cancer development through regulation of the epithelial-mesenchymal transition (EMT) and functions of p27 and RhoA signaling." (PMID 33250768, 2020). "Although many studies have demonstrated the roles of PTTG1 in breast cancer, the underlying mechanisms are still unclear." (PMID 32272902, 2020). "The results demonstrated that the levels of PTTG1 were associated with tamoxifen sensitivities of breast cancer cells." (PMID 32272902, 2020). "After the oncogenic roles of PTTG1 have been identified, many studies further elucidated the underlying mechanisms of PTTG1 in breast cancer." (PMID 32272902, 2020). "It is noteworthy that two of the genes that were found to predict poor survival of prostate and breast cancer patients in the present study (PTTG1 and COL1A2), form part of a 17-gene signature associated with metastases." (PMID 17183660, 2006). "Other studies have associated overexpression of PTTG1 and genetic instability in colorectal cancer, and it has been used as a prognostic marker in skin cancer and breast cancer." (PMID 32793179, 2020). "PTTG1 was associated with poor survival rates in breast cancer." (PMID 32272902, 2020). "Overexpressed PTTG1 could cause aneuploidy and promotes oncogenesis in breast cancer." (PMID 33777092, 2021). "Therefore, we speculate that the levels of PTTG1 might be associated with the cell cycle of breast cancer cells." (PMID 32272902, 2020). "In BC, PTTG1 levels are significantly higher than in normal tissue, suggesting its potential role in breast cancer pathogenesis." (PMID 40072059, 2025). "Pituitary tumor transforming gene 1 (PTTG1) has been demonstrated to promote proliferation, migration, and invasion of cancer cells and is a gene that promotes breast cancer development." (PMID 40454580, 2025). "The reports present evidence indicating that elevated expression of pituitary tumor-transforming gene-1 (PTTG1) promotes breast cancer malignancy by augmenting the breast CSC population and inducing EMT through the activation of the PI3K/AKT pathway." (PMID 38807590, 2024). "PTTG1 is also detected to be overexpressed in multiple cancers such as breast cancer, lung cancer, and gastric cancer." (PMID 37583701, 2023). "For instance, Yoon and colleagues have reported that PTTG1 promotes the development of breast cancer by the regulation of EMT and cancer stem cell populations." (PMID 32272902, 2020). "By using the TCGA breast cancer dataset, two genes including CCNA2 and CCNB2 were identified to be associated with the PTTG1." (PMID 32272902, 2020). "We further investigated the correlation of PTTG1 overexpression in distant metastasis-free survival (DMFS) of breast cancer patients using the Kaplan-Meier plot database." (PMID 33173433, 2020). "To further determine the mechanism of PTTG1-mediated breast cancer cell invasion, we determined the effect of PTTG1 on the regulation of MMP-2 and MMP-9 expression and activity in MDA-MB-231 cells." (PMID 33250768, 2020).
breast carcinoma (continued). "In the present study, we found that simvastatin markedly inhibited cell invasion in human breast cancer cell lines via down-regulating the expression of PTTG1, a key oncogenic gene involved in cancer invasion and metastasis." (PMID 33250768, 2020). "Mechanistically, we demonstrated that simvastatin inhibits PTTG1 expression through decreasing PTTG1 mRNA stability in breast cancer cells." (PMID 33250768, 2020). "Consistent with previous reports, we found that PTTG1 is highly expressed in malignant breast cancer cells." (PMID 33250768, 2020). "DMFS of breast cancer patients was highly correlated with PTTG1 overexpression with a hazard ratio (HR) of 1.79." (PMID 33173433, 2020). "GEO data set was applied to analyze the relationship between PTTG1 and survival status and the TCGA breast cancer dataset was used to explore its possible targets." (PMID 32272902, 2020). "In our previous research, PTTG1, the gene of human Securin, was detected with the most significant expression difference between human breast cancer and normal breast glandular tissue on basis of a cDNA microarray analysis involving 4000 cancer related genes." (PMID 32546141, 2020). "In 2015, another study initiated by Xiea finds that PTTG1 promotes the development of breast cancer by the regulation of p27, a gene that regulates the cell cycle." (PMID 32272902, 2020). "To substantiate the functional significance of PTTG1 in breast cancer malignancy, we determined the expression of PTTG1 in four types of different breast cancer cells, with different metastatic capacities." (PMID 33250768, 2020). "The present study demonstrated that the levels of PTTG1 were correlated with the survival status of patients with breast cancer." (PMID 32272902, 2020). "First, we explored the relationship between PTTG1 mRNA expression pattern and survival status of patients with breast cancer using the GSE22220 dataset." (PMID 32272902, 2020). "The breast cancer cells that were transfected PTTG1 overexpression plasmids have lower cell viabilities as compared to the breast cancer cells in the absence of PTTG1 plasmids transfection." (PMID 32272902, 2020). "Another study has revealed that PTTG1 induces tumorigenesis of breast cancer through regulating transforming growth factor β (TGFβ) mediated signaling pathway." (PMID 32272902, 2020). "Previous studies have revealed the oncogenic roles of PTTG1 in the tumorigenesis of many types of cancers including non-small cell lung cancer, hepatoma, prostate cancer, and breast cancer." (PMID 32272902, 2020). "In the present study, we found that statins potently inhibit PTTG1 expression in breast cancer cells, which led to a marked inhibition of cancer cell invasion." (PMID 33250768, 2020). "PTTG1, as an androgen responsive gene, acts in the progression of androgen‐induced prostate cancer, colorectal cancer, breast cancer, ovarian cancer, and bladder cancer." (PMID 32170852, 2020). "In 2012, Yoon and colleagues have demonstrated that PTTG1 is associated with the epithelial-mesenchymal transition (EMT) and is also correlated with the regulation of cancer stem cells in breast cancer." (PMID 32272902, 2020). "Estrogen-regulated PTTG1 promotes the development of breast cancer cells by the regulation of the cell cycle." (PMID 32272902, 2020). "Our results identified statins as novel inhibitors of PTTG1 expression in breast cancer cells and provide mechanistic insights into how simvastatin prevent breast cancer metastasis as observed in recent preclinical and clinical studies." (PMID 33250768, 2020). "Herein, we sought to investigate the effect of statins on the expression of pituitary tumor-transforming gene 1 (PTTG1), a critical gene involved in human breast cancer invasion and metastasis." (PMID 33250768, 2020). "Our results supported that estrogen regulated PTTG1 expression and PTTG1 reduced tamoxifen sensitivities of breast cancers." (PMID 32272902, 2020).
breast carcinoma (continued). "Among different statins, simvastatin has been shown to demonstrate better outcomes in patients with breast cancer, thus it was chosen to investigate the dose and time dependent effects of statins on PTTG1 expression in MDA-MB-231 cells." (PMID 33250768, 2020). "PTTG1 shRNAs were successfully employed to knock down the expressions of PTTG1 in the breast cancer cell line including MCF7 and T47D." (PMID 32272902, 2020). "Together, we for the first time identified statins as novel inhibitors of PTTG1 expression in breast cancer cells." (PMID 33250768, 2020). "We obtained coexpression profiles of PTTG1 with a strong cluster of the top 10% coexpressed genes across clinical breast cancer tissues from the METABRIC dataset." (PMID 33173433, 2020). "The expression level of PTTG1 in breast cancer samples was markedly higher than that in matched normal breast samples." (PMID 31011629, 2019). "Numerous investigations have shown that PTTG1 and -2 serve as two key oncogenes in a variety of human cancers, including breast cancer, lung cancer, pituitary adenoma, and esophageal squamous cell cancer." (PMID 31011629, 2019). "A recent report points out that PTTG1 promotes migration and invasion of breast cancer cells through activation of AKT." (PMID 27893422, 2017). "In our study of microarray expression data from 203 breast cancer patients, we analyzed the genes present in multiple signatures, and found three genes (MAD2L1, PTTG1 and BUB1) significantly associated with disease-free or overall survival." (PMID 26287798, 2015). "Expression of the PTTG1 gene was among the most significant components within the prognostic gene expression signature in prostate and breast carcinoma." (PMID 17183660, 2006). "PTTG1 may enhance cell growth in breast cancer by promoting cell proliferation through p27 nuclear exclusion, highlighting a novel mechanism in breast cancer tumorigenesis." (PMID 40072059, 2025). "Additionally, the tissue-specific functions of PTTG1 and its differential expression patterns across cancers such as hepatocellular carcinoma and breast cancer warrant more extensive study." (PMID 40072059, 2025). "Furthermore, miR-381-3p expression was found to be low and inversely correlated with PTTG1 expression in breast cancer tissues." (PMID 38807590, 2024). "PTTG1: PTTG1 may increase breast cancer (BC) cell growth through nuclear exclusion of p27, highlighting a novel molecular regulatory mechanism in breast cancer (BC) tumorigenesis." (PMID 37468832, 2023). "In addition, the prognostic values of PTTG1 were also reported in several tumors, such as breast carcinoma and prostate carcinoma." (PMID 35251171, 2022). "Previous research works have shown that high PTTG1 expression could enhance breast cancer malignancy by augmenting breast cancer stem cell population and epithelial mesenchymal transition in a manner dependent on activation of the PI3K/AKT pathway." (PMID 36060253, 2022). "Furthermore, it was reported that PTTG1 induced EMT in breast cancer cells by promoting AKT phosphorylation, which in turn, mediated Snail increase (a well-known E-CAD transcriptional repressor)." (PMID 36230799, 2022). "Pituitary tumor-transforming gene-1 (PTTG1), a ubiquitously expressed factor of transcription, is proven with the overexpression within several types of tumors, including lung carcinoma, ovarian carcinoma, prostate carcinoma, and breast carcinoma." (PMID 35251171, 2022). "PTTG1 is well known for promoting the growth of breast cancer." (PMID 36077657, 2022). "Interestingly, our data showed that the “TTP metabolism pathway” was correlated with PTTG1 expression in breast cancer development, which suggests that PTTG1 regulates TTP signaling in cancer progression." (PMID 33173433, 2020). "Furthermore, we determined the effects of statins on PTTG1 expression in MDA-MB-231 breast cancer cell line, which expresses a high level of endogenous PTTG1." (PMID 33250768, 2020).
breast carcinoma (continued). "In 2006, PTTG1 was identified as one of the mRNA biomarkers in patients with breast cancer." (PMID 32272902, 2020). "Overall, the results demonstrated that PTTG1 effected the cell viabilities of breast cancer cells." (PMID 32272902, 2020). "In addition, estrogen has been shown to promote breast cancer development through increasing PTTG1 expression." (PMID 33250768, 2020). "Our data revealed that “TTP metabolism” was correlated with PTTG1 expression, “glycolysis/gluconeogenesis” was associated with PTTG2 expression, and the “dCTP/dUTP metabolism” pathway was correlated with PTTG3 expression in breast cancer development." (PMID 33173433, 2020). "Our results are in part consistent with a recent report, in which Qi and colleagues identified overexpression of PTTG1 might serve as diagnosis and poor prognosis biomarkers in breast cancer." (PMID 32272902, 2020). "The survival analysis indicated that high PTTG1 expression was significantly associated with poor DMFS in all breast cancer patients, and in the luminal A and B subtypes, which implies that PTTG1 might play an oncogenic role in breast cancer." (PMID 33173433, 2020). "Overexpression of PTTG1 led to more breast cancer cells distributed in S phase." (PMID 32272902, 2020). "Increased expression of PTTG1 has been reported in proliferating cancer cells and various tumors including breast cancer, suggesting that PTTG may function in breast tumorigenesis." (PMID 33250768, 2020). "Studies have shown that PTTG1 is highly expressed in breast cancer and PTTG1 may increase breast cancer cell growth through the nuclear exclusion of p27." (PMID 33304656, 2020). "Interestingly, the results showed that overexpression of PTTG1 led to more breast cancer cells distributed in S phase." (PMID 32272902, 2020). "Mechanistically, we showed that both knockdown of PTTG1 expression and simvastatin treatment potently attenuated breast cancer cell invasion, presumably through inhibition of the expression of PTTG1 downstream target genes, such as MMP-2, MMP9, c-myc, FGF-2, and cyclin D3." (PMID 33250768, 2020). "PTTG1 has been demonstrated to be a key target of PTTG3P in both breast cancer and HCC8,11." (PMID 33298873, 2020). "Our in vitro study further supported the oncogenic roles of PTTG1 in breast cancer." (PMID 32272902, 2020). "Meanwhile, coexpression profiles of PTTG1 were identified from a public breast cancer database." (PMID 33173433, 2020). "Our findings also supported that PTTG3P may upregulate PTTG1 expression, thus functioning as an oncogene in breast cancer." (PMID 31011629, 2019). "PTTG1 was also found to enhance the migration and invasion of breast cancer cells." (PMID 27893422, 2017). "Since the effects of PTTG1 on breast cancer cells have been studied previously by Yoon at el." (PMID 26287798, 2015). "Breast cancers with higher PTTG1 levels are resistant to tamoxifen and fulvestrant." (PMID 21858218, 2011). "PTTG1 was proposed as a marker of breast cancer aggressiveness." (PMID 21858218, 2011). "Besides, PTTG1 affected cell cycle arrest of breast cancer cells." (PMID 32272902, 2020). "Finally, we explored the possible targets of PTTG1 in breast cancer." (PMID 32272902, 2020). "However, there are limited studies focusing on the regulation of PTTG1 in breast cancer." (PMID 32272902, 2020). "However, the breast cancer cells with PTTG1 overexpression showed lower cell viability." (PMID 32272902, 2020). "Notably, we identified that CCNA2 and CCNB2 were target genes of PTTG1 in breast cancer." (PMID 32272902, 2020). "Furthermore, our results suggest that simvastatin may be more beneficial for breast cancer patients with high PTTG1 expression." (PMID 33250768, 2020).